MIR155 (microRNA 155)
Synonyms: hsa-mir-155; MIRN155; miRNA155; mir-155
Gene: MicroRNA gene on chromosome 21 (25,573,980 to 25,574,044, forward strand). Ensembl gene ENSG00000283904.
Gene Ontology:
Biological process: miRNA-mediated post-transcriptional gene silencing
Cellular component: RISC complex
Homologues: Orthologues: chimpanzee ptr-mir-155 (98% identical), macaque mml-mir-155 (97% identical), rabbit MIR155 (97% identical), guinea pig MIR155 (94% identical), pig ssc-mir-155 (92% identical), mouse Mir155 (91% identical), rat Mir155 (91% identical), tropical clawed frog xtr-mir-155 (80% identical), zebrafish mir155 (68% identical).
Diseases named in the same sentence as MIR155 in open-access papers:
MIR155 is named in the same sentence as 22 diseases in open-access papers, as found by Europe PMC text mining. Sharing a sentence is not in itself a finding about the gene and the disease. The quoted sentences say what the papers report.
Arthritis (2 papers, 2015 to 2023). Inflammation of a joint. "Mir155-/- mice had mild arthritis similar to B6 mice, and DKO mice had severe arthritis, similar to Il10-/- mice." (PMID 26252010, 2015). "An elevated level of Mir155 in arthritis promotes M1 macrophage polarization and inflammation." (PMID 36598122, 2023).
Autoimmunity (2 papers, 2021 to 2022). The occurrence of an immune reaction against the organism's own cells or tissues. "Mir155, however, is essential in the development of autoimmunity, acting as an accurate controller of the Th17/Treg balance." (PMID 35941891, 2022). "In this manuscript, we have developed a novel screening assay to discover small molecules that can modulate Mir155 reporter as potential novel therapeutic avenues for inhibiting Th17 function and preventing autoimmunity." (PMID 34075120, 2021).
B-cell lymphomas (1 paper, 2024). "The LncRNA-SERB (ENST00000456917), also named as MIR155 host gene (MIR155HG), which can be transcriptionally activated by promoter insertion at a common retroviral integration site in B-cell lymphomas." (PMID 38641065, 2024).
cardiac hypertrophy (1 paper, 2022). "On the contrary, expression of MIR155 that promotes cardiac hypertrophy by targeting calcium signaling and inhibits angiogenesis showed a slight trend to increase in metformin-treated relative to non-treated groups, which aligns with the higher cardiomyocyte areas found in group M." (PMID 36359302, 2022).
carditis (1 paper, 2015). "Infected Mir155-/- mice developed moderate/severe carditis, had higher B. burgdorferi numbers, and had reduced Th1 cytokine expression in hearts." (PMID 26252010, 2015). "Interestingly, Mir155 was also upregulated in infected B6 heart tissue, a tissue known to display cytokine induction and carditis at this time point." (PMID 26252010, 2015).
gastric cancer (1 paper, 2023). A primary or metastatic malignant neoplasm involving the stomach. "Studies have shown that MIR155 host gene (MIR155HG) acts as an oncogene in several cancers, but the function and its mechanism of MIR155HG in gastric cancer (GC) is still poorly understood." (PMID 37324190, 2023).
leukemia (1 paper, 2015). A malignant (clonal) hematologic disorder, involving hematopoietic stem cells and characterized by the presence of primitive or atypical myeloid or lymphoid cells in the bone marrow and the blood. "While young Mir155-/- mice do not exhibit overt defects in development, mice constitutively over-expressing miR-155 spontaneously develop chronic inflammation and leukemia." (PMID 26252010, 2015).
Sepsis (1 paper, 2021). Sepsis is defined as life-threatening organ dysfunction caused by a dysregulated host response to infection. "To study survival, we applied the murine gold standard sepsis model of CLP (that was piloted to a mortality of 75%) to MIR155 knockouts." (PMID 33618730, 2021). "MIR155 overexpression was sufficient to induce spontaneous vascular leakage in zebrafish, augment pathological responses in cultured human endothelial cell monolayers and exacerbate the endothelial inflammatory response in murine sepsis." (PMID 33618730, 2021). "Conversely inhibition of MIR155 may improve vascular integrity and overall survival, making this microRNA a putative therapeutic target for further exploration in sepsis and related indications." (PMID 33618730, 2021). "Moreover, pharmacological inhibition or genetic depletion of MIR155 prevented breakdown of the vascular barrier and improved global outcome in animal models of systemic inflammation and sepsis." (PMID 33618730, 2021). "Therefore, future experiments will be required in order to explore the lack of protection against sepsis exhibited by MIR155 knockout mice." (PMID 33618730, 2021).
tumor (3 papers, 2016 to 2025). "miRNAs such as Mir155, Mir181, Mir92a, and Mir20a have been implicated in sustaining a tumor-promoting inflammatory milieu, with roles in immune regulation, macrophage polarization, and modulation of chemokine expression." (PMID 40869212, 2025). "Beyond tumor cell-autonomous effects, Mir155 has a key role in shaping the inflammatory milieu by regulating immune cells like myeloid-derived suppressor cells and tumor-associated macrophages, accentuating its involvement in tumor-promoting inflammation and metastasis." (PMID 40869212, 2025). "Moreover, MIR155 is overexpressed in HL and targets SMAD2 as well, supporting the role of SMAD2 as a tumor suppressor in this malignancy." (PMID 37428779, 2023).
cancer (2 papers, 2023 to 2025). A tumor composed of atypical neoplastic, often pleomorphic cells that invade other tissues. "The most potent of these variants may be mutations in well-known cancer-related miRNA genes, such as MIR16-2, MIR143, or MIR155, or mutations recurring in specific miRNA genes." (PMID 40867048, 2025).
infection (2 papers, 2015 to 2021). The state of being infected such as from the introduction of a foreign agent such as serum, vaccine, antigenic substance or organism. "Numbers in bold indicate statistically significant difference in Mir155 expression after infection, and were determined by Student’s t-test (p<0.05, n≥5 mice per group)." (PMID 26252010, 2015). "In order to determine if Mir155 was upregulated in heart and skin tissue, infected B6 and Il10-/- mice with B. burgdorferi were analyzed at 3 weeks post-infection, a time point consistent with the peak for NF-κB dependent responses in B. burgdorferi-infected mice." (PMID 26252010, 2015). "At 4 weeks post-infection, Th1-associated Ifng, Cxcl10, and Il12 transcript levels were significantly higher in joints of Il10-/- and DKO mice, compared to transcript levels in joints of B6 and Mir155-/- mice." (PMID 26252010, 2015). "Cxcl1 and Cxcl2 regulated by Mir22 and Mir155 are chemokines which signal through CXC receptor 2 to attract neutrophils to the place of inflammation, which is essential to control tissue infection." (PMID 34527215, 2021). "Mir155 primary transcripts were also elevated in joints of Il10-/- (but not B6) mice at 4 weeks post-infection." (PMID 26252010, 2015).
neurodegenerative disease (1 paper, 2019). A disorder of the central nervous system characterized by gradual and progressive loss of neural tissue and neurologic function. "MIR155 overexpression was previously implicated in downregulation of complement factor H (CFH) expression in AD and other neurodegenerative diseases which in turn may prevent spontaneous immune system activation." (PMID 30636644, 2019).
MIR155 also shares sentences with these, for which no sentence is quoted: periodontitis (2 papers); atherosclerosis (1); Cerebral ischemia (1); cholangiocarcinoma (1); gastrointestinal tumors (1); glioma (1); infarction (1); Obesity (1); osteoarthritis (1); tuberculosis (1).